ACE (angiotensin I converting enzyme)
Diseases named in the same sentence as ACE in open-access papers (continued):
Sharing a sentence is not in itself a finding about the gene and the disease.
Alzheimer disease (continued). "Clinical studies have shown an elevated ACE activity in various brain regions of Alzheimer’s disease (AD) patients." (PMID 23008812, 2012). "However, the brains of some Alzheimer’s disease patients showed upregulation of the renin-angiotensin system, which led to deleterious effects, and ACE inhibition was beneficial." (PMID 40988601, 2025). "Beyond APOE, Alzheimer’s disease is associated with MTHFR and ACE polymorphisms." (PMID 38790930, 2024). "Therefore, measurement of ACE activity/levels in the blood, after adjustment for hormonal status and ACE genotype, may help to identify individuals with the lowest levels of tissue ACE expression who may be at risk for the development of late-onset Alzheimer’s disease." (PMID 38255267, 2024). "The upregulation of these proteins by ACE inhibitors may contribute to the amelioration of cognitive deficits in Alzheimer’s disease/dementia, as well as the clinically observed deceleration of functional decline in Alzheimer’s patients." (PMID 37630190, 2023). "Therefore, the inhibition of ACE activity was suggested to benefit patients with Alzheimer’s disease and/or dementia." (PMID 37630190, 2023). "Overall, these findings indicate that ACE inhibitors may be a promising avenue for developing effective treatments for Alzheimer’s disease." (PMID 37630190, 2023). "Metastudies by different research groups could not conclude whether ACE insertion/deletion polymorphism has a significant impact on Alzheimer’s disease patients, suggesting that ACE might play a minor role in Alzheimer’s disease." (PMID 37630190, 2023). "In addition, ACE inhibition by systemic administration of captopril ameliorated cognitive function and neurodegeneration in several Alzheimer’s disease (AD) models by reducing the expression of complement protein C3." (PMID 36104755, 2022). "Genetic evidence has supported a protective effect of cerebral ACE against Alzheimer disease (AD)." (PMID 36046424, 2022). "Moreover, in Alzheimer’s disease (AD) models, where glial inflammation occurs and is thought to contribute to the propagation of the disease, increased levels of Ang II and ACE have been detected." (PMID 29765306, 2018). "Interestingly, this metalloprotease is involved in Alzheimer’s disease since human ACE increases degradation and cleavage of Aβ." (PMID 26932723, 2016). "Notably, enzymatic removal of the first five Aβ residues is performed by ACE66 as we showed earlier, which can potentially link ACE to Alzheimer’s disease." (PMID 26898943, 2016). "Polymorphisms within the apolipoprotein-E (APOE), Methylenetetrahydrofolate reductase (MTHFR) and Angiotensin I-converting enzyme (ACE) genes has been associated with cardiovascular and cerebrovascular disorders, Alzheimer’s disease and other complex diseases in various populations." (PMID 24679048, 2014). "In addition, whereas BBB-impermeant ACE inhibitors have little effect on Alzheimer’s disease symptoms, BBB-permeant inhibitors such as perindopril significantly delay the symptomatic progression in Alzheimer’s disease patients." (PMID 24289788, 2013). "ACE inhibitors may increase the risk of schizophrenia, Alzheimer’s disease, and psoriasis but do not affect COVID-19 risk." (PMID 39567981, 2024). "ACE inhibitors might increase the risk of psoriasis, schizophrenia, and Alzheimer’s disease but did not affect COVID-19." (PMID 39567981, 2024). "Although ACE polymorphisms are a risk factor for Alzheimer’s disease and age-onset diseases that may contribute to mortality, the ACE DD genotype but not the ID genotype was in favor of exceptional longevity over the mortality expected in older people." (PMID 36834822, 2023). "Moreover, it was suggested that the ACE-mediated control of the renin-angiotensin system may play a role in the cognitive decline of patients with Alzheimer’s disease." (PMID 37630190, 2023).
Alzheimer disease (continued). "However, ACE also catalyzes the formation of the vasoconstrictor angiotensin II (Ang II) from angiotensin I. The actions of Ang II within the central nervous system are also of increasing interest in the context of Alzheimer’s disease (AD)." (PMID 29176997, 2017). "ACE may also be important in Alzheimer’s disease because it is capable of cleaving amyloid-β." (PMID 24618270, 2014). "We next discuss current hypotheses to explain the disorders of Alzheimer’s disease (AD) and Parkinson’s disease (PD), as well as research efforts focused on the use of angiotensin converting enzyme (ACE) inhibitors and angiotensin receptor blockers (ARBs), in their treatment." (PMID 24298267, 2013). "Therefore, another possibility is that ACE inhibition does not causally influence risk to the conditions per se, but some of their common phenotypic expressions, such as cognitive decline, which is common to both schizophrenia and Alzheimer’s disease." (PMID 40281223, 2025). "For example, dipeptide VY can significantly inhibit the activity of the angiotensin-converting enzyme (ACE); tripeptide WIR has a potential anti-Alzheimer’s disease effect; and dipeptide YL exhibits antidepressant-like activities in mice." (PMID 35711539, 2022). "Supermeres are highly enriched with cargo involved in multiple cancers (glycolytic enzymes, TGFBI, miR-1246, MET, GPC1 and AGO2), Alzheimer’s disease (APP) and cardiovascular disease (ACE2, ACE and PCSK9)." (PMID 34887515, 2021). "The mean values for ACE activity (relative units) ± SEM were: controls 154.9 ± 9.972, vascular dementia 154.6 ± 29.37, Alzheimer’s disease 165.3 ± 12.70." (PMID 24618270, 2014). "Additionally, it has been shown that the amelioration of cognitive deficits mediated by ACE inhibitors in Alzheimer’s disease is independent of the antihypertensive effect." (PMID 37630190, 2023). "The role of ACE (CD 143) is not yet fully established in Alzheimer’s disease." (PMID 27875990, 2016). "We have now investigated the relationships between ACE, ET1, VEGF and the two myelin proteins, to determine the extent to which the vasoregulatory factors protect from or contribute to white matter injury in Alzheimer’s disease, vascular dementia and control brains." (PMID 24618270, 2014). "Elevated concentrations of ACE, angiotensin II, and AT1 receptors in the cerebral cortex of patients with AD suggest that enhanced activation of the RAS may inhibit the release of acetylcholine in the cortex and contribute to the development of Alzheimer’s dementia." (PMID 35207180, 2022). "First, proteomics screening and statistical analysis show that blood biomarkers LGALS3BP, ACE, and POSTN effectively screen for cerebral amyloid depositions and clinically diagnose Alzheimer’s disease, but the theoretical basis is still lacking." (PMID 37446296, 2023). "For example, in the cerebral cortex of patients with Alzheimer’s disease, a decrease in the ACE2 activity and a negative correlation with the ACE activity was found; further, changes in the AT II/AT 1-7 ratio were not consistent." (PMID 34796023, 2021). "White matter ACE activity did not correlate significantly with the MAG:PLP1 ratio and was similar in Alzheimer’s disease, vascular dementia and controls." (PMID 24618270, 2014).
Nephropathy (124 papers, 2008 to 2026). A nonspecific term referring to disease or damage of the kidneys. "Hyperglycemic diabetic patients with genetically high ACE levels are at increased risk of developing nephropathy and the disease evolves more severely in these patients." (PMID 31316987, 2019). "Taken together, in type 1 diabetes with nephropathy, the I allele increases the responsiveness to the antiproteinuric (renoprotective) effect of ACE inhibitor therapy." (PMID 25587546, 2014). "Although the data from our study failed to confirm an increased risk for development of DN in T2DM, previous studies from Japan, the USA, and Iran showed association between ACE-DD genotype and/or D-allele and the risk for nephropathy in T2DM." (PMID 24282791, 2013). "Recent studies have implicated association between angiotensin converting enzyme (ACE) insertion/deletion (I/D) gene polymorphism and nephropathy." (PMID 20535249, 2009). "Taken together, our data show that renal ACE deficiency protects against AAI-induced nephropathy." (PMID 36520238, 2023). "Thus, it appears that renal ACE deficiency may convey protective effects against aristolochic acid-induced nephropathy, triggering the question as to the underlying molecular mechanisms." (PMID 36520238, 2023). "Studies have shown that renin-angiotensin system may play an important role in the development of nephropathy in type II DM, and thus, the angiotensin converting enzyme (ACE) polymorphism may be a potential predictor for development of nephropathy in type II DM." (PMID 20535249, 2009). "Early recognition and management of AS with ACE inhibitors and SGLT2i are vital to prevent irreversible kidney damage and other complications." (PMID 40462774, 2025). "Once again, these collective findings demonstrated the broader renoprotection offered by BM-MSCs-eRLX + GFP over BM-MSCs-eGFP or ACE inhibition against HS-induced nephropathy." (PMID 39443975, 2024). "The excessive activation of the ACE regulatory axis and inhibition of the ACE 2 regulatory axis can lead to increased blood pressure and kidney damage." (PMID 38472752, 2024). "Simultaneous administration of CDDP with an ACE inhibitor (enalapril) or an ARB (telmisartan) worsened kidney damage." (PMID 38799728, 2024). "By contrast, if ACE inhibitors have been shown to slow kidney disease progression in patients with nephropathies, especially if proteinuria is present, the role of ACE inhibitors in slowing the progression of ADPKD needs to be clarified." (PMID 37893495, 2023). "The present study shows that renal ACE deficiency protects against AAN, a new type of nephropathy that has recently evoked major research efforts due to its widespread occurrence and its often malignant course." (PMID 36520238, 2023). "Adherence to treatment guidelines improved in the treatment group, particularly for the examination of nephropathy status (or intake of ACE inhibitors) and for ensuring regular ophthalmologic examinations." (PMID 35716315, 2023). "The administration of NSAIDs in patients with nephropathy treated with ACE-inhibitors, diuretics or anti-coagulant therapy should be avoided and requires close monitoring of renal function and the hemocoagulative status." (PMID 36975594, 2023). "HbA1c screen, nephropathy screen (or ACE-inhibitor prescription), retinopathy screen, lipid panel, and prescription." (PMID 37533530, 2023). "Elevated ACE excretion into urine was also found in diabetic patients with overt nephropathy, and even different fragments of the N domain of ACE were found." (PMID 36979933, 2023). "ACE inhibitors reduce oxidative stress, improve endothelial dysfunction, and help to delay the progression of retinopathy and nephropathy." (PMID 35328284, 2022). "Reduced BP was associated with increased plasma renin and markers of kidney damage (mice) in SCD, as well as significantly decreased plasma ACE concentrations and ACE enzyme activity." (PMID 35113975, 2022).
Nephropathy (continued). "It is known that ACE inhibitors during radiotherapy reduce the occurrence of radiation pneumonitis, nephropathy and optic neuropathy." (PMID 33336040, 2020). "A polymorphism of the angiotensin-converting enzyme gene caused by an insertion/deletion (ACE/ID) modifies the systemic and renal activity of the RAAS, which was recognized to be a trigger of kidney damage." (PMID 32823966, 2020). "It should also be borne in mind that allergic phenomena are observed even with medications traditionally used in the treatment of nephropathies, such as ACE inhibitors." (PMID 31023272, 2019). "Nephropathy develops faster in mice having three ACE gene copies and a moderate increase in ACE level, when the mice are rendered diabetic." (PMID 31316987, 2019). "We then processed renal tissue to identify the expression and distribution of kallikrein, ACE and neutral endopeptidase 24.11 as well as markers of kidney damage." (PMID 30618804, 2018). "The clinical importance becomes apparent when realizing that ACE-inhibitors still are the only medication for diabetic patients with nephropathy in order to delay progression." (PMID 28281693, 2017). "Together, the findings of these studies indicate that increases in the ACE/ACE2 ratio induced via the ACE/Ang II/AT1 axis have a significant influence on the development of severe kidney damage." (PMID 29157100, 2017). "Clinical evidence suggests that telmisartan, the PPARγ ligand ARB, is more potent than other ARBs or ACE inhibitors at slowing the development of nephropathy." (PMID 20613959, 2010). "In hypertensive T1DM or T2DM patients with microalbuminuria or overt nephropathy, both ACE inhibitors and ARBs protected against the progression of renal disease independent of BP reduction." (PMID 20441574, 2010). "We recently developed a novel approach to characterize ACE in tissue and blood—ACE phenotyping—which may be useful for improved characterization of urinary ACE in patients with nephropathy." (PMID 36979933, 2023). "Implementation of this comprehensive strategy with the attainment of improved glycemic control, use of ACE- or AT II1-blockers (RAS-blockade), and statin treatment reduced the risk of nephropathy, progression to end-stage kidney disease, and CV mortality in the STENO-2 trial." (PMID 37240483, 2023). "At present, only the ACE inhibitor captopril is approved for the therapy of nephropathy associated with type 1 diabetes and the angiotensin II receptor blocker (ARB) losartan for the therapy of nephropathy associated with type 2 diabetes." (PMID 35967126, 2022). "In addition, it should be pointed that a diet high in salt enhances ACE activity in healthy normotensive rats and then alters the ACE/ACE2 balance leading to kidney damage." (PMID 34385922, 2021). "Independent variables were ACE inhibitor therapy, sulfonylurea therapy, dosage of sulfonylurea, nephropathy, A1C levels, eGFR-MDRD value, minutes of physical activities, reporting hypoglycemia in the 7-day diary, SD, CV%, GMI and percentage of time spent in specific ranges." (PMID 32151247, 2020). "Moreover, a beneficial effect of ACE inhibitors has been suggested in many studies on retinopathy and nephropathy." (PMID 28373993, 2017). "Other prior studies have reported three- to fivefold increases in urinary ACE activity in patients with upper urinary tract infections and renal calculi in patients with chronic glomerulonephritis and nephrotic syndrome and in diabetic patients with nephropathy." (PMID 36979933, 2023). "In radiation injury, several decades of research support the usage of angiotensin converting enzyme (ACE) inhibitors for mitigation of a range of radiation-induced toxicities including: acute hematopoietic injury, pneumonitis, cardiac fibrosis, optic neuropathy, and nephropathy." (PMID 37275232, 2023).
Nephropathy (continued). "Thus, quantification of WT1 and ACE mRNAs in blood exosomes reflects the degree of albuminuria and the severity of nephropathy in DN patients, suggesting these mRNAs could serve as predictors of DN progression." (PMID 34246281, 2021). "In addition, since DN patients were in a good state of renal function with normal eGFR, we could assume that DN patients were in the early phase of nephropathy, and blood EVsWT1 and ACE mRNAs might be good biomarkers for diagnosis of early DN." (PMID 34246281, 2021). "Considering the negative impact of SCD associated nephropathy on the prognosis and the potential interest of an early nephroprotective treatment with angiotensin converting enzyme (ACE) inhibitors, an accurate screening of glomerular hyperfiltration is essential." (PMID 22866669, 2012). "It has been reported that some single nucleotide polymorphisms (SNPs) of the angiotensin converting enzyme (ACE) gene and the endothelial nitric oxide synthase (eNOS) gene are associated with the development of systemic lupus erythematosus (SLE) and the progression of nephropathy." (PMID 20540812, 2010). "RAS inhibitors, such as angiotensin-converting enzyme (ACE) inhibitors and angiotensin II receptor blockers (ARBs), help control blood pressure and reduce proteinuria, slowing kidney damage." (PMID 40337581, 2025). "Whether renal ACE deficiency also protects against nephropathy has not yet been investigated." (PMID 36520238, 2023). "Angiotensin-converting enzyme (ACE) inhibitors and angiotensin II type 1 receptor blockers (ARBs) are already known to have an anti-inflammatory effect, to decrease kidney damage in ADPKD and lower KYNA synthesis in the kidney." (PMID 36788192, 2023). "Axis overactivation regulated by ACE and axis inhibition regulated by ACE2 led to elevated blood pressure and kidney damage." (PMID 36235721, 2022). "There has been little progress in treating DKD since angiotensin-converting enzyme (ACE) inhibitors and angiotensin II receptor blockers (ARBs) were shown to delay progression of nephropathy over 20 years ago." (PMID 29629372, 2018). "In adult rodent UUO models angiotensin-converting enzyme (ACE) inhibitors and AT1 receptor inhibitors given prophylactically (for the duration of obstruction) are beneficial in alleviating nephropathy." (PMID 28286898, 2018). "Boldine prevented the increase in ACE-1 and TGF-β in 2K1C rats, suggesting that boldine reduces kidney damage." (PMID 29941815, 2018). "We missed the opportunity for early detection of proteinuria and we failed to prescribe ACE inhibitors to slow the progression of kidney damage at an earlier stage." (PMID 24955116, 2014). "Indeed, inhibition of RAS by angiotensin-converting enzyme (ACE) inhibitor or angiotensin II (Ang II) type-1 receptor (AT1R) blocker has been shown to suppress the development and progression of nephropathy in both type-1 and type-2 diabetic subjects." (PMID 25143788, 2014). "Interventions aimed at providing renoprotection, such as ACE-inhibition or statin therapy, can reduce the renal MAPK expression, suggesting that increased renal MAPK expression is involved in the pathophysiology of kidney damage." (PMID 22523682, 2012). "It is of significance to note here that a recent Interventional study aimed at blockade of the renin-angiotensin system (RAS) with ACE-inhibitors or ARBs, in patients with type 1 diabetes, did not slow nephropathy progression." (PMID 23028588, 2012). "The importance of RAAS blockade in the treatment of nephropathy has been clearly established, although the renal benefits of ARBs and ACE inhibitors seem to be independent of their blood pressure lowering effects." (PMID 20613959, 2010). "In addition to being resistant to RAAS enzymes, Elabela could indeed restore the ACE/ACE2 balance and exert cardiorenal protective effects against salt-driven hypertension and kidney damage." (PMID 34385922, 2021).
Nephropathy (continued). "The higher prescription rate of ACE inhibitors among men can potentially be explained not only by the higher CVD comorbidity, but also by the higher prevalence of nephropathy in men than in women and the protective effect of ACE inhibitors towards progression of nephropathy." (PMID 22838970, 2012). "Recently, a large study on the renal and retinal effects of angiotensin II inhibition in 256 normoalbuminuric and normotensive patients with T1DM revealed that both ACE inhibition and ARB delayed the progression of retinopathy, but not nephropathy." (PMID 20441574, 2010). "This study aimed to assess the expression levels of ACE, ELMO1, and WT1 mRNAs in the blood extracellular vesicles (EVs) of DN patients and diabetic patients without nephropathy (DM group) in comparison to healthy controls and investigate their correlations with the severity of DN." (PMID 34246281, 2021).